APOE (apolipoprotein E)
Diseases named in the same sentence as APOE in open-access papers (continued):
Sharing a sentence is not in itself a finding about the gene and the disease.
glomerulosclerosis (9 papers, 2012 to 2023). A hardening of the kidney glomerulus caused by scarring of the blood vessels. "In our study, collagen type IV staining was significantly suppressed in ApoE−/−/OPN−/−HD mice compared with ApoE−/−HD mice, indicating that osteopontin deficiency contributes to reduced glomerulosclerosis and lipid accumulation." (PMID 27353458, 2016). "Mesangial cell proliferation and mesangial matrix accumulation have been associated with various forms of kidney disease and in animal models a deficiency of APOE may lead to glomerulosclerosis." (PMID 22874105, 2012). "Immunohistochemistry showed that complement C9 and ApoE were highly expressed in both KW nodules and solidified glomerulosclerosis compared with class I glomeruli or primary FSGS." (PMID 33633132, 2021). "The present data showed that ApoE, a key regulator of lipid and lipoprotein homeostasis, was present at significantly higher concentrations in solidified glomerulosclerosis." (PMID 33633132, 2021). "Lipids are known to play a role in glomerulosclerosis and apoE abnormalities seem to have a genetic or epigenetic factor in several renal diseases." (PMID 25353171, 2014). "Moreover, consistent with the results of single glomerular proteomics, the percentage of the glomerular complement C9 and ApoE-positive area was higher in solidified glomerulosclerosis than in KW nodules." (PMID 33633132, 2021). "Additionally, single glomerular proteomics, combined with immunohistochemistry, revealed that complement C9 and apolipoprotein E were highly expressed in solidified glomerulosclerosis." (PMID 33633132, 2021). "Because patients with solidified glomerulosclerosis had higher cholesterol level and glomerular deposition of ApoE than those without solidified glomerulosclerosis, it is likely that glomerular deposition of apolipoproteins partly reflects higher circulating concentrations of these substances." (PMID 33633132, 2021).
gout (9 papers, 2010 to 2022). A condition characterized by painful swelling of the joints, which is caused by deposition of urate crystals. "It has been noted that the ApoE polymorphism was associated with development of gout and primary hyperuricemia." (PMID 25890021, 2015). "For example, previous studies showed that in the pathogenesis of hyperuricemia, ApoE polymorphisms in patients with gout were reported to be associated with reduced renal excretion of urates." (PMID 25890021, 2015). "The presence of the APOE-ε2 allele in patients with gout is associated with reduced renal excretion of urates." (PMID 25356596, 2014). "Besides that, ApoB and ApoE also exerts a key role in the resolution of acute gout through coating MSU crystal." (PMID 30863362, 2019).
influenza (9 papers, 2011 to 2025). An acute viral infection of the respiratory tract, occurring in isolated cases, in epidemics, or in pandemics; it is caused by serologically different strains of viruses (influenzaviruses) designated A, B, and C, has a 3-day incubation period, and usually lasts for 3 to 10 days. "Among proteins related to multiple infections, 30 out of 38 were associated with influenza, including total APOE, APOE3, APOE4 (apolipoproteins), DEFB4A (an antimicrobial peptide) and RAG1 (a VDJ recombination activator)." (PMID 39143319, 2024). "Second, in a study on apoE knockout mice, influenza vaccination promoted the formation of smaller and more stable atherosclerotic plaques through an immunoresponse." (PMID 35665329, 2022).
lung adenocarcinoma (9 papers, 2017 to 2025). A carcinoma that arises from the lung and is characterized by the presence of malignant glandular epithelial cells. "Collectively, our findings not only clarify the critical role of APOE+ macrophages in shaping the immune landscape and prognosis of lung adenocarcinoma, but also provide a validated, practical risk model for individualised patient prognostication and clinical management." (PMID 40736341, 2025). "Serum ApoE is associated with lymph node metastasis in lung adenocarcinoma patients." (PMID 31275318, 2019). "The immunoregulatory functions and clinical implications of APOE+ macrophages within the tumour microenvironment of lung adenocarcinoma remain incompletely defined." (PMID 40736341, 2025). "Suppression of ApoE in lung adenocarcinoma cells reduced colony formation, chemotherapy resistance, cell proliferation, and metastasis." (PMID 31275318, 2019). "It was also reported that high expression of ApoE promotes cancer proliferation and migration and contributes to an aggressive clinical course in patients with lung adenocarcinoma." (PMID 31275318, 2019). "Moreover, ApoE overexpression contributes to cisplatin resistance and can serve as a poor prognostic biomarker for patients with lung adenocarcinoma." (PMID 31275318, 2019). "APOE is also an OS responsive gene with antioxidative properties; however, recent studies have demonstrated that APOE overexpression promotes cancer proliferation and migration and contributes to an aggressive clinical course in patients with lung adenocarcinoma." (PMID 29552057, 2017). "Novel signature genes of TAMs, including triggering receptor expressed on myeloid cells 2 (TREM2), CD81, macrophage receptor with collagenous structure (MARCO), and apolipoprotein E (APOE), were discovered in lung adenocarcinoma using scRNA-seq." (PMID 36154923, 2022).
myocardial ischemia (9 papers, 2014 to 2024). A disorder of cardiac function caused by insufficient blood flow to the muscle tissue of the heart. "In addition, SMY also could improve left ventricular structure, morphology, function, blood flow, infarct area, myocardial damage, and ROS accumulation to varying degrees in ApoE−/− mice, which had a potential protective effect in DEP-aggravated AS with myocardial ischemia." (PMID 36506810, 2022).
neuropathy (9 papers, 2014 to 2025). A disorder affecting the nervous system that manifests with pain, tingling, numbness, and/or muscle weakness. "In this review, a focus was given on the differential contribution of the different APOE variants to neuropathies and ND clinical outcomes." (PMID 39596597, 2024). "Collectively, these studies provided support for the hypothesis that apolipoprotein E (APOE)-driven lipid imbalance and fluctuations synergistically aggravated the progression of neuropathy." (PMID 41572967, 2025). "Moreover, in a model of peripheral nerve damage-induced neuropathy it has been shown that metformin increases the level of ApoE, a 34 kDa glycoprotein that is a major determinant of lipid transport and metabolism." (PMID 24955774, 2014). "Apolipoprotein E polymorphism in T2DM patients with or without neuropathy." (PMID 41488146, 2025).
post-traumatic stress disorder (9 papers, 2015 to 2023). An anxiety disorder precipitated by an experience of intense fear or horror while exposed to a traumatic (especially life-threatening) event. "Consistent with peripheral apoE affecting the CNS, plasma apoE levels are positively correlated with severity of post-traumatic stress disorder (PTSD), a disorder afflicting the CNS." (PMID 35884888, 2022).
rheumatoid arthritis (9 papers, 2013 to 2022). A chronic, systemic autoimmune disorder characterized by inflammation in the synovial membranes and articular surfaces. "It has been demonstrated that apoE has a major impact on longevity, and apoE may also play a role in other pathological conditions including cancer, rheumatoid arthritis, and macular degeneration." (PMID 27143969, 2016). "We aimed to investigate the associations of apoE genotypes with adipokines, inflammatory parameters, and cardiovascular disease (CVD) risks in rheumatoid arthritis (RA) patients." (PMID 33297350, 2020).
sarcopenia (9 papers, 2019 to 2025). Progressive decline in muscle mass due to aging which results in decreased functional capacity of muscles. "Furthermore, there appears to be a role for CpG islands within the APOE gene to act as signals for protein binding and chromatin remodeling, and this might also affect the risk of both sarcopenia and AD with advancing age." (PMID 38790190, 2024). "The NPI and BDS-ADL scores and the prevalence of APOE ε4 carriers and sarcopenia were significantly higher in the ADD group than in the other groups." (PMID 30862124, 2019). "Another gene potentially involved in resistance to sarcopenia is APOE (apolipoprotein E)." (PMID 40869996, 2025). "The APOE ε4 variant also predisposes to slower walking speed in individuals with mild cognitive impairments (MCI), and slow walking speed is an underlying feature of sarcopenia." (PMID 38790190, 2024).
temporal lobe epilepsy (9 papers, 2014 to 2026). A localization-related (focal) form of epilepsy characterized by recurrent seizures that arise from foci within the temporal lobe, most commonly from its mesial aspect. "A bioinformatics study discovered that the ε4 variation of the apolipoprotein E (APOE) gene is associated with both temporal lobe epilepsy (TLE) and SLE." (PMID 39340433, 2024). "In relation to the last one, it has been shown that APOE ε4 allele increases the risk and is associated with an earlier onset of temporal lobe epilepsy." (PMID 39886338, 2024). "A high level of APOE was found to be associated with an earlier onset of temporal lobe epilepsy and was observed in TLE patients’ plasma." (PMID 39063177, 2024). "Apolipoprotein E (APOE) gene has been implicated as one of the genes susceptible to temporal lobe epilepsy (TLE), but the association is inconsistent." (PMID 26945380, 2016). "The role of APOE genotype in risk for development of Alzheimer's is well known, and the potential additive effect of having APOE ε4 allele(s) on the risk for developing Alzheimer's in risk-conferring neurological conditions such as in head trauma and in temporal lobe epilepsy has been reported." (PMID 25859183, 2015). "In summary, our study provides valuable insights into the complex interplay between sex, APOE genotype, and cognitive performance in temporal lobe epilepsy." (PMID 39886338, 2024). "In temporal lobe epilepsy, hippocampal APOE is markedly upregulated predominantly in microglia." (PMID 41085045, 2026). "Recently, some researchers have extended the study of the APOE impact to other conditions, such as cardiovascular diseases, traumatic brain injury, multiple sclerosis and temporal lobe epilepsy." (PMID 39886338, 2024). "A meta-analysis suggested that the APOE ε4 isoform was a genetic factor that might influence the age at onset of temporal lobe epilepsy." (PMID 24621278, 2014). "A structurally related PET tracer [18F]FTTM was not only demonstrated to provide sufficient brain uptake for the imaging of neuroinflammation in the rat model of temporal lobe epilepsy, but also to outperform [18F]FDG in the imaging of the ApoE Mouse model of atherosclerotic plaques." (PMID 36674884, 2023).
Hydrocephalus (8 papers, 2016 to 2025). Hydrocephalus is an active distension of the ventricular system of the brain resulting from inadequate passage of CSF from its point of production within the cerebral ventricles to its point of absorption into the systemic circulation. "Cxcl1/KC (keratinocyte-derived chemokine) as the intermediating cytokine of hydrocephalus in ApoE-knockout/APOL1-G1 mice." (PMID 39803526, 2024). "The development of communicating hydrocephalus and resulting early death in ApoE-KO; BAC/APOL1-G1 mice was a novel and unexpected finding." (PMID 39803526, 2024). "We cannot exclude the remote possibility that the BAC insertion site contributes to some portion of hydrocephalus development in ApoE-KO; BAC/APOL1-G1 mice." (PMID 39803526, 2024). "Presence of CMB, APOE ε4 carrier status, hydrocephalus, and seizures correlate with worse neurocognitive outcomes in pediatric cancer survivors, enriched with CNS tumors exposed to radiation." (PMID 35814456, 2022). "Unexpectedly, 21% (3/14) of ApoE-KO/APOL1-G1 mice developed hydrocephalus." (PMID 39803526, 2024). "While APOL1-G1 expression in ApoE-KO mice did not worsen cardiovascular disease phenotypes, we uncovered hydrocephalus as a novel APOL1 risk allele-mediated phenotype." (PMID 39803526, 2024). "Several pathways may be involved in the development of hydrocephalus in the ApoE-KO; BAC/APOL1-G1 mouse model." (PMID 39803526, 2024). "In summary, our work shows that CMBs, WMLs, APOE ε4 carrier status, hydrocephalus and/or seizures at baseline may serve as markers for long-term cognitive dysfunction in pediatric cancer survivors, especially in patients with CNS tumors previously treated with radiation." (PMID 35814456, 2022). "In choroid plexus epithelium of ApoE-KO; BAC/APOL1-G1 mice, immunohistochemistry confirmed higher expression of phospho-NKCC1 and phospho-SPAK compared with wildtype mice, as also reported in other hydrocephalus mice." (PMID 40459058, 2025). "Unexpectedly, 21% (3/14) of ApoE-KO; BAC/APOL1-G1 mice developed hydrocephalus." (PMID 40459058, 2025). "While APOL1-G1 expression in ApoE-KO mice did not worsen CVD phenotypes, we uncovered hydrocephalus as a novel APOL1 risk allele-mediated phenotype." (PMID 40459058, 2025). "Low penetrance of hydrocephalus in ApoE-KO; BAC/APOL1-G1 mice was not clear." (PMID 40459058, 2025). "However, ~20% of ApoE-KO; BAC/APOL1-G1 mice developed hydrocephalus and required euthanasia." (PMID 39803526, 2024). "Low penetrance of hydrocephalus in ApoE-KO; BAC/APOL1-G1 mice was not clear, however, unknown environmental factors might have contributed." (PMID 39803526, 2024). "ApoE-KO; BAC/APOL1-G1 mouse with hydrocephalus (n=1) and ApoE-KO mouse without hydrocephalus (n=1) in the littermates were used for the analysis." (PMID 39803526, 2024).
hyperuricemia (8 papers, 2010 to 2023). An abnormally high level of uric acid. "With the continuous in-depth studies on ApoE gene polymorphism and the popularization of clinical investigations, it was found that patients with different ApoE gene polymorphisms have different left ventricular remodeling progressions to hyperuricemia." (PMID 36620636, 2022). "This study assessed association between ApoE polymorphisms with hyperuricemia and uric acid metabolism in Uygur men, Xinjiang, China." (PMID 25890021, 2015). "In the current study, we aimed to understand the possible association of ApoE with risk of hyperuricemia in Uygur population." (PMID 25890021, 2015). "These ApoE genotypes were associated with the highest level of uric acid and hyperuricemia incidence (p < 0.001)." (PMID 25890021, 2015). "ApoE E4 was associated with a slightly higher risk of primary hyperuricemia, whereas ApoE E2 was associated with reduced risk of primary hyperuricemia and LDL-C level." (PMID 25890021, 2015). "ApoE E4 was associated with a slight increased risk of primary hyperuricemia, whereas ApoE E2 was associated with protection against primary hyperuricemia and LDL-C in Uygur men in China." (PMID 25890021, 2015). "Our current study showed that frequencies of the ApoE genotype and alleles were unique in this population and associated with hyperuricemia risk." (PMID 25890021, 2015). "The distribution of ApoE alleles and genotype frequencies in the Uygur male is unique, and was associated with hyperuricemia risk." (PMID 25890021, 2015). "The possible association of ApoE and risk of hyperuricemia has been widely investigated in different populations." (PMID 25890021, 2015). "In the present study we observed that APOE gene polymorphism is associated with hyperuricemia in Chinese subjects." (PMID 25356596, 2014). "Univariate analysis of the association between APOE polymorphism, metabolic parameters and hyperuricemia." (PMID 25356596, 2014). "At present, the correlation between APOE polymorphisms and hyperuricemia remains elusive in China, especially among individuals in an area inhabited by ethnic minorities." (PMID 25356596, 2014). "ApoE gene polymorphism is associated with the risk of hyperuricemia in various populations." (PMID 36620636, 2022). "For example, previous studies reported that gene polymorphism in Uygur Chinese may be correlated with hyperuricemia such as ApoE E4, IL-8, IL-1RL1, IL-18 and SLC17A1 genes." (PMID 32238146, 2020). "However, our current study is just proof-of-principle and much more data are needed to confirm the link of ApoE polymorphisms with the risk of primary hyperuricemia." (PMID 25890021, 2015). "Thus, in this study, we aimed to detect the frequency of ApoE polymorphisms in Uygur males and assess how ApoE polymorphisms were associated with primary hyperuricemia risk." (PMID 25890021, 2015). "Therefore, it is reasonable to explore the connections between APOE gene polymorphism and hyperuricemia." (PMID 25356596, 2014). "Therefore, the objective of this study was to assess the genetic associations of APOE polymorphisms and hyperuricemia in a Chinese population." (PMID 25356596, 2014). "Multivariate analysis of the independent association between APOE polymorphism and hyperuricemia." (PMID 25356596, 2014). "Our data support the conclusion that hyperuricemia alone is an exacerbating factor of AAA formation in ApoE-KO mice." (PMID 36710339, 2023). "Distribution of ApoE genotypes was significantly different in hyperuricemia patients from the healthy controls (p < 0.001)." (PMID 25890021, 2015). "Our data showed that although ApoE 3/3 genotype is the most common genotype in Uygur, the frequency of E2/2 genotype is lower than the E4/4 genotype in both control and hyperuricemia subjects." (PMID 25890021, 2015).
hyperuricemia (continued). "A total of 474 hyperuricemia patients and 518 healthy male controls were recruited from the Health Screening Center, Uygur region of Xinjiang, China and subjected to ApoE genotyping using a multiplex amplification refractory mutation system PCR." (PMID 25890021, 2015). "This study aims to assess the genetic associations between Apolipoprotein E (APOE) polymorphisms and hyperuricemia in a Chinese population." (PMID 25356596, 2014). "In conclusion, this study is the first to report that the APOE ε2 allele is positively associated with SUA and could be an independent risk factor for hyperuricemia in a Chinese population." (PMID 25356596, 2014). "The APOE-ε2ε3 genotype and the APOE-ε2 allele are associated with serum uric acid levels in Chinese subjects, indicating that individuals carrying the APOE-ε2 allele have a higher risk of hyperuricemia than non-carriers." (PMID 25356596, 2014). "We found that hyperuricemia itself increased the expansion of the diameter of the abdominal aorta, the incidence of AAA and the degradation of elastin fibers in the aorta in ApoE-KO mice." (PMID 36710339, 2023). "Moreover, we also compared other biochemical parameters with different ApoE genotypes between hyperuricemia patients and controls and found that both groups of subjects with the ApoE2 allele had a lower uric acid and LDL-C level than those with the ApoE3 allele and ApoE4 allele (p <0.05)." (PMID 25890021, 2015). "Furthermore, the induction of hyperuricemia alone enhanced the abundance of MMP-9, URAT1, and p-ERK1/2 expression in the abdominal aorta in ApoE-KO mice compared with control mice (2.37-fold, n = 6, P < 0.05; 1.92-fold, n = 6, P < 0.05; and 2.51-fold, n = 6, P < 0.05)." (PMID 36710339, 2023). "Therefore, in this population, it is possible that ApoE genotype, but not BMI and DBP, is independently associated with hyperuricemia." (PMID 25356596, 2014).
macular degeneration (8 papers, 2015 to 2023). Loss of vision in the central portion of the retina (macula), secondary to retinal degeneration. "In line with this, it must also be noted that the APOE genotype can influence peripheral diseases such as cardiovascular diseases or macular degeneration." (PMID 36153580, 2022). "Life-extending SNPs near APOE, FOXO3 and FGD6 are all associated with increased measures of macular degeneration." (PMID 32678081, 2020).